GFAP (glial fibrillary acidic protein)
Diseases named in the same sentence as GFAP in open-access papers (continued):
Sharing a sentence is not in itself a finding about the gene and the disease.
status epilepticus (17 papers, 2013 to 2025). Status epilepticus is defined as a continuous seizure lasting more than 30 min, or two or more seizures without full recovery of consciousness between any of them. "Seizure-induced GFAP overexpression reflects a first step in astrocyte activation and hypertrophy and is significant three days after status epilepticus." (PMID 36350974, 2022). "In rats in status epilepticus, hippocampal mIns was strongly correlated with staining for two astrocyte markers, glial fibrillary acidic protein (GFAP) and S100b." (PMID 26578948, 2015). "However, co-localization with the astrocyte marker GFAP increased sharply at later stages after status epilepticus (24 h and 72 h post-status epilepticus) with ~50% of GFAP-positive cells being positive for GFP." (PMID 28235423, 2017). "Additionally, we noted more intense GFAP labeling in all of the examined brain areas, which is frequently observed following status epilepticus." (PMID 23724051, 2013). "Pre-treatment with Tualang honey reduced neuroinflammation by reducing the elevation of TNF-α, IL-1β, glial fibrillary acidic protein, allograft inflammatory factor 1 and COX-2 in the cerebral cortex, cerebellum and brainstem of kainic acid-induced status epilepticus rat." (PMID 33435215, 2021). "Interestingly, GFAP and p-ERK1/2 were found to be co-expressed in the hippocampi of mice subjected to PIL-induced status epilepticus after 6 h." (PMID 34690772, 2021). "Both ALX/FPR2 and ChemR23/ERV1 immunostaining was increased in GFAP-positive astrocytes but not in CD11b-positive microglia 72 h post-status epilepticus (n = 8) (colour micrographs)." (PMID 30307467, 2018). "While P2Y1 was detectable at low levels in cortical neurons and microglia under control conditions and following status epilepticus, no co-localization was observed using the astrocyte markers GFAP and S100β in vehicle-injected control mice and in mice subjected to status epilepticus." (PMID 32009961, 2019).
type 2 diabetes (17 papers, 2016 to 2026). "In summary, increased GFAP plasma values in patients with acute coma identify intracranial hemorrhage with high diagnostic accuracy." (PMID 38581002, 2024). "Only one prior study investigated circulating GFAP levels in persons with type 2 diabetes but used an assay unable to detect serum GFAP in both patients and controls." (PMID 40192786, 2025). "Increased GFAP is a sign of an astrocyte’s response to brain damage, which is made worse by type 2 diabetes." (PMID 41150802, 2025). "In addition, patients with very early GFAP measurements after coma onset (< 30 min; n = 14) showed a comparable diagnostic accuracy to patients with longer or unknown times from symptom onset to blood withdrawal (ROC area under the curve 1.000 [1.000–1.000], p < 0.001)." (PMID 38581002, 2024). "Increased levels of autoantibodies against GFAP have further been found in plasma from patients with Type 2 Diabetes (T2D)." (PMID 39275164, 2024). "Noticeably, a reduction in GFAP protein was observed in samples from type 2 diabetes temporal cortex only." (PMID 37351595, 2023). "High GFAP expression notably upregulated pathways related to riboflavin metabolism, O-glycan biosynthesis, and taurine and hypotaurine metabolism, while downregulating primary immunodeficiency, basal cell carcinoma, and maturity-onset diabetes of the young." (PMID 41009659, 2025). "Similarly, an increase in the number of GFAP-positive astrocytes was found in rats with transient hypoglycemic coma." (PMID 38026658, 2023). "Thus, NONRATT021972 siRNA treatment may block P2X7 activation in the DRG to inhibit the up-regulation of TNF-α and GFAP and to decrease the pain behaviors of type 2 diabetic rats." (PMID 27107575, 2016). "Our data show that type 2 diabetes differentially affects the numbers of AVP- and VIP-expressing neurons and GFAP-ir astroglial cells in the SCN, each of which could affect the daily rhythmicity of the SCN biological clock machinery." (PMID 31327049, 2019).
colitis (16 papers, 2011 to 2025). Inflammation of the colon. "In light of TBI inducing glial activation and neuroinflammation in the hippocampus, it is possible that similar mechanism could underlie the reduced GFAP observed in the hippocampus in DSS-induced colitis model mice." (PMID 32047521, 2020). "Neuroinflammation in the brain in response to acute colitis was further explored by assessing astrogliosis and microgliosis based on GFAP and Iba1 immunofluorescence in brain tissue sections and by Western blotting." (PMID 40457749, 2025). "ES 50 mg/kg (11.75 ± 2.02) and Au@ES 50 mg/kg (8.53 ± 1.45), as well as dexamethasone (7.71 ± 1.41), decreased the labeling (p < 0.05) when compared to the colitis group, in terms of GFAP-positive cells per field." (PMID 39199130, 2024). "Quantitatively, immunolabeling for GFAP was increased in the colitis group (17.63 ± 3.76) when compared to the control group (2.75 ± 0.81)." (PMID 39199130, 2024). "In chronic DSS-induced colitis, expression of the pan-reactive astrocyte marker glial fibrillary acidic protein (Gfap) and the A1 astrocyte marker complement factor 3 (C3) was increased in the hippocampus and cortex." (PMID 36232412, 2022). "The fluorescence intensity of GFAP decreased in colonic mucosa of mice after colitis (compared with the control group; p< 0.01)." (PMID 36189321, 2022). "Our findings show that GFAP expression indicative of reactive glia is reduced in the DSS-induced colitis mice and worse in the CSE knockout mice." (PMID 36189321, 2022). "Patients with colitis Crohn also had an increase in GFAP and GDNF expression in inflamed colonic biopsies, but less impressive than patients with UC." (PMID 21235736, 2011). "However, at 5.5 months, the DSS colitis down-regulates GFAP gene expression specifically in Tg2576 animals (C57BL6-DSS and Tg2576-DSS)." (PMID 38773640, 2024). "Altered expression of S100B and GFAP has been reported in several intestinal inflammatory disorders in humans, such as inflammatory bowel disease, celiac disease, and postoperative colitis." (PMID 37834076, 2023). "In addition, colitis-induced decreases in GFAP, C3 protein, and S100A10 expression were more significant in CSE KO mice than in WT mice." (PMID 36189321, 2022). "Still, colitis exacerbated the decrease of GFAP, C3, and S100A10 protein expression." (PMID 36189321, 2022). "In the NaHS treatment, colitis-induced GFAP fluorescence intensity was enhanced considerably." (PMID 36189321, 2022). "However, the fluorescence intensity of GFAP in colonic mucosa of CSE knockout mice induced by colitis was significantly decreased compared with that of WT mice." (PMID 36189321, 2022). "For example, R. intestinalis may function in the modulation of the gut–brain axis by reducing the level of colonic 5-hydroxytryptamine (5-HT), inhibiting the expression of glial fibrillary acidic protein (GFAP), and alleviating the depression-like behaviors in colitis model mice." (PMID 34881193, 2021). "Additional evidence in murine models of colitis demonstrates an altered expression of inflammatory modulators, including cyclo-oxygenase 2 (COX-2) and glial fibrillary acidic protein (GFAP), in the brain." (PMID 37274195, 2023). "In mice with CMI and colitis, VNS significantly reversed the increases in blood–brain barrier permeability, infarct volume, activation of Iba-1+ microglia and GFAP+ astrocytes, and TNF-α level in mice with colitis and CMI." (PMID 37484689, 2023). "The DSS+CMI group exhibited greater numbers of Iba1+ cells in the infarct core (P < 0.001) and GFAP+ cells in the peri-infarct regions than those in the CMI group (P < 0.001), which indicates that colitis enhanced neuroinflammation in the acute phase of CMI." (PMID 30319530, 2018).
colitis (continued). "Given recent work on the neurogenic potential of EGCs52,59, it is notable that we saw upregulation of the canonical glial markers GFAP and S100β specifically in cured mice, as well as PLP1, which corresponds to the subset of glial cells that differentiate into neurons in the DSS colitis model." (PMID 38782898, 2024). "However, depletion of the GFAP+ enteric glia had no measurable effect on DSS-induced colitis severity." (PMID 33282743, 2020).
neuroblastoma (16 papers, 2009 to 2025). Neuroblastoma (NB) is the most common solid, extracranial childhood tumor. "Knockdowns of several kinases that could participate in the observed GFAP hyperphosphorylations decreased protein aggregation and associated physiological declines in C. elegans and in human neuroblastoma cells expressing amyloid precursor protein." (PMID 35890250, 2022). "The highest percentage of synaptophysin-positive cells was observed with serum-free medium, a medium developed for the culture of neuroblastomas, whereas ‘Izal’ medium harboured the lowest relative percentage of synaptophysin and GFAP-positive cells." (PMID 36178902, 2022). "In line with our findings, previous studies have reported bFGF to increase the gene and protein expression of p75 NGFR in the human neuroblastoma cell line and expressions of GFAP mRNA in astrocytes." (PMID 32575426, 2020). "Using our SC-like cells conditioned medium collected on day 10 (because of the highest expression of SC makers, such as S100, GFAP, and MBP) successfully induced the neurite outgrowth in a neuroblastoma cell line, SH-SY5Y cells." (PMID 33322066, 2020). "We pursued AD-specific phosphorylations by RNAi knockdowns of upstream kinases that may target the modified GFAP sites, each of which resulted in a marked reduction in amyloid deposition by human neuroblastoma and glioma cells in vitro." (PMID 35890250, 2022). "Furthermore, the decrease in GFAP expression was clearly observed in CAPE-treated neuroblastoma cells as compared with their untreated counterpart." (PMID 33244299, 2020). "Similar to human neural progenitor cells, human neuroblastoma cells are characterized by a high content of SOX2+ cells and co-expression of the β-III-tubulin and GFAP." (PMID 37047534, 2023). "In addition, cells were co-stained for the glial marker GFAP, as previous findings reported glial trans-differentiation induced by retinoic acid in HIF-1α inhibited neuroblastoma cells." (PMID 34557995, 2022). "By 5 days in 3D cultures, neuroblastoma cells in collagen gels showed up-regulation of neuronal markers and PROM1 (CD133, prominin) and slight down-regulation of glial markers (e.g. OLIG2 and GFAP) in 3D as compared to 2D." (PMID 32321995, 2020). "Additionally, the neuronal differentiation of neuroblastoma cells was confirmed by Western blotting using antibodies against NSE, GFAP and GAPDH." (PMID 31712567, 2019). "Expression of GFAP was reduced (nonsense versus shRNA CgA, 1.0±0.1 versus 0.02±0.01, P<0.05), whereas expression of PMP22 (1.0±0.02 versus 3.3±0.5, P<0.05) and SERPINF1 (1.0±0.1 versus 3.1±0.5, P<0.01) was increased in the shRNA CgA transfectants compared to nonsense control neuroblastoma cells." (PMID 30833285, 2019).
retinal ischemia (16 papers, 2009 to 2025). A ischemic disease that involves the retina. "Modulates the overexpression of GFAP in in vivo models of retinal ischemia and inhibits overactivation of NF-κB, IL-1β, and Cox-2 in Müller cells." (PMID 34439904, 2021). "Consistent with this interpretation, increases in GFAP expression have also been found following transient choroidal and/or retinal ischemia." (PMID 27485271, 2016). "Notably, GFAP-labeled astrocytes peaked at 24 h in a mouse model of retinal ischemia-reperfusion, which is consistent with the phenomenon observed in vitro." (PMID 40880987, 2025). "After preconditioning, slighter GFAP immunoreactivity was observed after retinal ischemia compared with the untreated group, suggesting that the mechanism of preconditioned retinal ischemia may be related to Müller cells in the retina." (PMID 38502592, 2024). "The immunofluorescence results showed that GFAP expression was increased and reorganized after retinal ischemia-reperfusion injury, indicating reactive MGC gliosis, while rapamycin treatment could clearly mitigate MGC gliosis." (PMID 36078054, 2022). "Retinal ischemia results in reactive gliosis, which is characterized by hypertrophy, proliferation, and upregulated expression of the intermediate filament, including glial fibrillary acidic protein (GFAP), in Müller cells." (PMID 26689280, 2015). "GFAP over-expression in Müller cells is an early marker of retinal injury in retinal ischemia." (PMID 20652025, 2010). "Induced retinal ischemia in mice was followed by an elevated expression of HIF-1α and glial fibrillary acidic protein (GFAP)." (PMID 33466614, 2021). "Recently, using the same GFAP-IκBα-dn mice employed in the present study, we demonstrated that NF-κB-regulated NAD(P)H oxidase in astrocytes is a crucial mediator of oxidative stress in a model of retinal ischemia and inhibition of its activity reduces damage by preventing RGC loss." (PMID 22963651, 2012). "Moreover, immunocytochemistry of glial fibrillary acidic protein (GFAP), glutamine synthetase (GS) and aquaporin-4 (AQP4) peptides on retinal sections were performed to study glial cell reactivity, glutamate metabolism and water accumulation, respectively after retinal ischemia." (PMID 22053184, 2011).
scrapie (16 papers, 2010 to 2025). A fatal disease of the nervous system in sheep and goats, characterized by pruritus, debility, and locomotor incoordination. "The mechanisms associated with the expression of GFAP in scrapie-affected medullae, along with the molecules involved in prion deposition or spongiform degeneration, remain unclear." (PMID 21629698, 2011). "Welch’s t-test shows statistical significance between the two populations for both scrapie prion and GFAP expression, thus confirming that the prion-tg37 population is diseased." (PMID 39958854, 2025). "PrPSc deposits, spongiosis (HE staining), astrogliosis (GFAP) and microgliosis (Iba1), were evaluated in two areas of the CNS previously reported to be the most affected by scrapie: the medulla oblongata at the level of the obex and the thalamus." (PMID 40597437, 2025). "Similar to the western blotting results, the astrocyte marker GFAP was upregulated in ME7 scrapie-infected mice." (PMID 40302732, 2025). "The interaction of GFAP and PrPc/PrPsc was identified through ligand blotting from hamster brain homogenates and verified by Co-IP and immunostaining from normal and scrapie-infected brains and recombinant proteins." (PMID 32992764, 2020). "Immunofluorescent assays (IFAs) illustrated that the signals of AQPs colocalized with those of the GFAP positive proliferative astrocytes, and more interestingly, appeared to overlap also with the signals of PrP in the brains of scrapie-infected mice." (PMID 31814527, 2019). "The levels of GFAP were also higher in the brainstem-cerebellum of scrapie-infected mice prior to PrPres accumulation at 70 dpi (P = 0.0041) and showed a tendency to higher levels in the cortical region at 90 dpi, as observed previously." (PMID 25183307, 2014). "The program analyzes the continuous effect of scrapie related lesions, measured as PrPSc deposition, GFAP immunostaining and spongiosis, on individual gene expression." (PMID 21629698, 2011). "A generalized increase in the expression of the astroglial marker glial fibrillary acidic protein (GFAP) was observed in the brains of the scrapie-affected sheep (P<0.01)." (PMID 21629698, 2011). "Spongiosis, PrPSc deposition and GFAP immunoreactivity were consistent with the features of classical scrapie." (PMID 21629698, 2011). "Comparing the prp2 morphant with the mouse scrapie model revealed 5 genes in common: GFAP, CD9 antigen (CD9), solute carrier family 14 member 1 (SLC14A1), heat shock 22kDa protein 8 (HSPB8) and syndecan 4 (SDC4)." (PMID 21042590, 2010). "When extending the comparisons between differentially expressed genes to include two mouse scrapie models only 1 gene (GFAP) is in common for all 4 studies and two when comparing the 3 mammalian (GFAP, ABCA1)." (PMID 21042590, 2010). "Additionally, there was an increase in GFAP expression in the brains of scrapie-affected mice, with the cerebrum and cerebellum showing the most intense staining." (PMID 38698886, 2024). "Therefore, to enhance visualization of GFAP+ astrocytes we induced reactive gliosis by infecting GFP/WT heterozygous mice with scrapie prions, and visualized the brains at middle stages of disease (week 41 of a 54 week incubation period)." (PMID 24752288, 2014). "In accordance with this finding, we observed a significant overexpression of the metallothionein 2A (MT2A) gene in scrapie medullae, which was positively associated with prion deposition but not with GFAP immunostaining." (PMID 21629698, 2011). "GFAP immunostaining was significantly increased in the CA1 and CA3 pyramidal cell layers from the scrapie-infected versus control sheep." (PMID 35408945, 2022). "The assays of the double-stained IFA with AQP1 antibody together with GFAP antibody showed a large amount of colocalization of AQP1 singals (red) with GFAP-positive cells (green), particularly in the brain slices of scrapie-infected mice." (PMID 31814527, 2019).
scrapie (continued). "Compared to the control retinas, an increased expression of GFAP was observed in the IPL and ganglion cell layer from all scrapie retinas, indicating Müller cell gliosis." (PMID 21639947, 2011). "In addition, the astrocyte marker GFAP was also significantly reduced in nattokinase- and lumbrokinase-treated ME7 scrapie-infected mice." (PMID 40302732, 2025). "The samples were digested in proteinase-K (PK) to determine the level of scrapie prion expression and non-digested otherwise to find the expression of GFAP and alpha-tubulin." (PMID 39958854, 2025). "For example, gliosis and increased GFAP were observed in the terminal stage of a mouse scrapie model, but not in the earlier stages." (PMID 31924264, 2020). "GFAP was found to be expressed more in the brain of scrapie-infected mice as compared with non-infected mice." (PMID 32992764, 2020). "However, GFAP was significantly higher expressed (p < 0.05) in the ME7 scrapie-infected mice compared with the negative control mice, indicating an upregulation of neuroinflammation." (PMID 39105172, 2024). "In the current study, none of the target genes (GFAP, SAA3, CXCL10, CD14, S100A9, and IL1B) associated with the acute phase response and inflammation were differentially expressed in the hippocampus of animals with and without scrapie." (PMID 31924264, 2020). "The results showed a non-significant difference in GFAP expression at 5 months (p = 0.47) in the SW02-treated ME7 scrapie-infected mice compared with the untreated ME7 scrapie-infected mice." (PMID 39105172, 2024).